INS (insulin)
Diseases named in the same sentence as INS in open-access papers (continued):
Sharing a sentence is not in itself a finding about the gene and the disease.
diabetes (continued). "Since insulin replacement inhibits or reverses these neurological deficits in diabetes animals, these results support the emerging and expanding hypotheses regarding the important role of insulin in the CNS, especially for hippocampal neurons." (PMID 22988465, 2012). "In ob/ob mice in which miR-375 was deleted, a marked decrease in beta-cell mass resulted in severe insulin-deficient diabetes not found in ob/ob miR-375+ mice." (PMID 23326263, 2012). "Indeed, the early seminal discovery that insulin crystals contain zinc facilitated a supportive role for this cation in diabetes." (PMID 23304467, 2012). "Several other zinc transporters, although not directly associated with diabetes, are implicated in insulin-mediated signaling and glycaemic control in animal models and humans." (PMID 23304467, 2012). "A higher incidence of MetS among insulin- or oral agent-treated patients could be attributable to their longer duration of diabetes, younger age at onset, and poorer metabolic control than in noninsulin-treated diabetes." (PMID 22474593, 2012). "Since hippocampal neurogenesis is coupled with expression of NeuroD1, the expression (and the secretion) of insulin in newborn neurons via the NeuroD1 transcription factor may be upregulated in a treatment that promotes adult neurogenesis in diabetes patients." (PMID 22988465, 2012). "Furthermore, BABR was reported to improve obesity, insulin sensitivity and glycemic control in diabetes mellitus mouse model." (PMID 22952571, 2012). "Diabetes mellitus is characterised by defects in insulin release or/and insulin sensitivity." (PMID 23243452, 2012). "Therefore, the low plasma insulin levels observed in the STZ-induced diabetes is expected to lower the activation of Akt, as demonstrated in this study." (PMID 23239980, 2012). "In fact, only one-third of insulin resistant obese individuals develop type 2 diabetes mellitus." (PMID 23110196, 2012). "Visualization of cornerstones in diabetes self-care (ie, diet, insulin dosage, physical activity, and pre- and postprandial glucose measurements all transformed into one picture) in the mobile diary was found to be an important educational tool through reflections in action." (PMID 22868871, 2012). "We hypothesised that in insulin treated diabetes, patients with higher endogenous insulin secretion will have a lower rise in glucose after meals and will respond less to prandial insulin." (PMID 22681724, 2012). "Type-2 diabetes accounts for ∼90% of all diabetes cases and it results from the metabolic disorders of insulin resistance (diminished sensitivity of the target tissues to insulin action) and β-cell failure (reduced ability of the pancreatic β-cells to produce sufficient insulin)." (PMID 22860063, 2012). "Together, this suggests that insulin, which is particularly elevated in premature type 2 diabetes mellitus, may be involved in the induction of SERCA2a mRNA expression and may be an early step in the pathogenesis of diabetic cardiomyopathy." (PMID 22621761, 2012). "When the patients were stratified based on their minimum BG levels, the frequency of diabetes and insulin treatment, SAPS II, SD of the mean BG, coefficient of variation, and Hermanides' metric were higher in the two hypoglycemic groups as compared with patients without hypoglycemia." (PMID 23062226, 2012). "Furthermore, participants with a high HbA1c were more likely to use diabetes medications, in particular insulin and sulfonamides, have a higher BMI and systolic blood pressure and were more likely to have co-morbidities." (PMID 22719972, 2012). "Furthermore, TSH did not correlate significantly with body mass index, fasting plasma glucose, hemoglobin A1C, insulin level or insulin resistance index in patients with diabetes in a Pakistani study." (PMID 23300866, 2012).
diabetes (continued). "Maintaining fitness is associated with a reduction in the risk factors for heart disease (high blood pressure and cholesterol) but not on risk factors for diabetes (insulin levels)." (PMID 22693553, 2012). "Thus, the modeling and the formal description of s.c. insulin transport is important for the effectiveness of modern diabetes control strategies." (PMID 24278682, 2012). "A consequence of diabetes, mostly of type 2 diabetes, is insulin resistance and chronic peripheral hyperinsulinemia, accompanied by downregulated insulin transport into the brain and its subsequent deprivation from insulin beneficial effects." (PMID 22500228, 2012). "The merging of the three significantly effected networks generated a complex network with regulatory hubs formed by inflammation related genes (e.g. TNF-α, NF-κB), kinases (e.g. AKT, PI-3 kinase), and transcriptional regulators (HNF4A, EGR1, Jnk) as well as diabetes related genes (Insulin, Ins1)." (PMID 22606220, 2012). "Taken together, our results suggest that hBMSCs-VEGF induce reversion of diabetes mainly by induction of endogenous β-cell regeneration through the generation of a favorable microenvironment mediated by the activation of the Insulin/IGF1 receptor/PI-3K/AKT pathway." (PMID 22879915, 2012). "Diabetes mellitus is a term employed to describe a metabolic disorder characterized by persistent hyperglycemia with disturbances of carbohydrate, fat, and protein metabolism resulting from defects in insulin secretion, insulin action, or both." (PMID 23056144, 2012). "Our subjects had type 1, not type 2, diabetes controlled on insulin and likely did not have the associated vascular risk often seen in type 2 diabetes." (PMID 22745753, 2012). "However, IL-6 also reflects the low-grade chronic inflammatory state that characterizes diabetes per se, the increased level of insulin resistance, and the increase in visceral adipose tissue, all of them present in the metabolic syndrome." (PMID 22924123, 2012). "Advances in research, that is, diabetes gene therapy and human insulin-producing cell therapy, may personalize treatment and make cure possible." (PMID 23882374, 2012). "Thirty people were excluded from the analysis population (N = 3031) due to receiving insulin for >12 months before study entry (n = 23), having type 1 diabetes (n = 3) or diabetes due to pancreatitis (n = 2) or pregnancy (n = 1) and having no time between starting insulin and study entry (n = 1)." (PMID 22519930, 2012). "Diabetes mellitus is an endocrine and metabolic disorder characterized by chronic hyperglycemia, dyslipidemia, and protein metabolism that result from defects in both regulations of insulin secretion and/or insulin action." (PMID 22849553, 2012). "In addition to the “insulin regulation and diabetes” gene set, we identified several other enriched modules comprised of differentially upregulated genes in response to SF, including “mitochondrion and oxidative phosphorylation” and “proteasome” gene sets." (PMID 22629440, 2012). "Hypoglycemia is one of the key acute complications of insulin therapy in diabetes treatment." (PMID 22969729, 2012). "Diabetes mellitus is a chronic disorder in the metabolism of carbohydrates, proteins, and fat due to absolute or relative deficiency of insulin secretion with/without varying the degree of insulin resistance." (PMID 22593683, 2012). "The primary engineering challenges to the widespread adoption of closed-loop control as a viable therapeutic option for diabetes include system connectivity, the accuracy of subcutaneous glucose sensing, and the speed of action of subcutaneously injected insulin." (PMID 24278682, 2012). "Nineteen patients were receiving diabetes medication, which could influence blood levels of insulin, glucose, and adiponectin concentration in this study." (PMID 21450081, 2011).
diabetes (continued). "The majority of people managing their diabetes with insulin correctly identified the steps to be taken in the event of low blood sugar, although individuals with cognitive impairment, who formed approximately one quarter of this group, were significantly more likely not to know what to do." (PMID 21166853, 2011). "Extensive epidemiological data have shown that diabetes is correlated with arterial calcification and higher insulin level could predicate arterial calcification independently." (PMID 22194983, 2011). "Among all participants, a higher number of type 2 diabetes risk alleles associated with a higher prevalence of diabetes (P=0.011) and higher serum concentration of glucose (P<0.016) but not insulin (P=0.450)." (PMID 21191145, 2011). "This could be demonstrated by further studying the effect of local insulin on the reduction of fatty acid elongases observed in rats with untreated short-term diabetes." (PMID 22046295, 2011). "In both the NF and NP groups, the history of diabetes was longer for patients using insulin." (PMID 21978180, 2011). "However, there were some differences in patient characteristics among groups of patients according to insulin prescribed, including diabetes duration, duration of OHA treatment, and FBG levels, but age and BMI were comparable." (PMID 21631903, 2011). "Additionally, a number of changes not evident at the one month time point were prevented from occurring with continued diabetes by insulin therapy." (PMID 21575160, 2011). "Understanding the diverse roles of glucose and insulin – energy supply and modulators of signalling cascades – and delineating glucose and insulin signalling pathways should facilitate prevention and drug discovery research to control obesity, diabetes and cancer." (PMID 21179032, 2011). "Furthermore, it has been seen before that a mutation can cause opposite effects on insulin secretion in early versus later life, since a HNF4A mutation causes hyperinsulimea in utero and then later causes diabetes in adulthood." (PMID 22073261, 2011). "Insulin is the drug of choice for management of diabetes with HIV." (PMID 21232158, 2011). "Diabetes duration also varied between patients receiving the different insulins and was longest in those receiving insulin detemir, which may have influenced efficacy outcomes." (PMID 21631903, 2011). "Top ten pathways affected by diabetes and reversed by ocular insulin administration." (PMID 22046295, 2011). "Higher levels of diabetes distress were associated with a higher frequency of depressive symptoms occurrence, negative attitudes toward insulin treatment, difficulties with the regulation of the blood glucose, and lower levels of emotional well-being." (PMID 22195273, 2011). "Embryonic stem (ES) cells and the newly developed induced pluripotent stem (iPS) cells are an ideal source for generating insulin-producing cells (IPCs) that could be used to treat diabetes." (PMID 22013504, 2011). "Therefore, human studies suggest that insulin secretion defect participates in the abnormal glucose tolerance observed in adult offspring exposed to maternal diabetes during fetal life." (PMID 22110471, 2011). "We will examine many of the common features of diabetes and AD to determine how they might interact and also address the issue of using diabetic medication and/or insulin as AD therapy." (PMID 22654727, 2011). "Therefore, generation of new beta cells either in vitro or in vivo is a high priority issue in diabetes treatment, and the identification of factors regulating the expansion of insulin-producing cells has potential importance for the treatment of diabetes." (PMID 21897861, 2011). "The present pieces of evidence designate that CDK5 might be a potential drug target for the regulation of glucose-stimulated insulin secretion in the treatment of diabetes mellitus." (PMID 22028710, 2011).
diabetes (continued). "Insulin resistant states, like obesity and diabetes, are typically associated with higher rather than lower concentrations of FFAs, secondary to decreased insulin-mediated suppression of lipolysis from adipose stores." (PMID 21857944, 2011). "A microarray analysis of the retinal transcriptome changes of diabetic rats and diabetic rats that received local insulin or phloridzin treatments revealed 983 genes were significantly affected greater than 1.2 fold (statistically significant with p<0.05) by diabetes." (PMID 22046295, 2011). "It now is believed that certain systemic diseases, such as diabetes mellitus, can contribute to neurodegeneration through the effects of chronic hyperglycemia/insulin resistance resulting in protein glycation, oxidative stress and inflammation within susceptible brain regions." (PMID 22332001, 2011). "Management of diabetes mellitus is based upon mechanisms which increase insulin secretion." (PMID 20981320, 2011). "The immediate post surgical outcome is unpredictable: disturbance in glucose homeostasis still remains (persistent hypoglycemia in about 50% of patient, insulin-requiring diabetes in 20% of patients during the post-surgical period) but usually in a more manageable manner than before surgery." (PMID 21967988, 2011). "GLUT4 protein levels may therefore play a role in the pathology behind type 2 diabetes mellitus among subgroups of patients, and this may explain the heterogeneous response to insulin treatment." (PMID 22114711, 2011). "Furthermore, a combination of both insulin and ozone therapy even further reversed the effects of diabetes mellitus in comparison to monotherapy." (PMID 22185664, 2011). "However, this first step in introducing prandial insulin therapy may provide a starting point for advancing to full basal–bolus treatment for those needing further intensification given individual clinical requirement based on diabetes duration, age and risk of macrovascular disease." (PMID 21679291, 2011). "More specifically, the second stage of the multi-purpose allele after recombinase conversion could be used for the conditional knockout of PTBP1 in pancreatic β-cells only in order to test the role of this gene in insulin granule biogenesis and diabetes." (PMID 21423341, 2011). "Therefore, although the treatment of diabetes is obviously important, insulin therapy for glycemic control should be carefully considered in those elderly patients." (PMID 21978180, 2011). "We previously showed that systemic insulin therapy could restore retinal insulin signaling and prevent retinal cell death induced by diabetes." (PMID 22046295, 2011). "One popular hypothesis to the effect of diabetes on bone is through insulin, acting as a bone anabolic factor." (PMID 21772974, 2011). "that high frequency of blood glucose measurement would be associated with lower HbA1c when controlled for important child characteristics: frequency of problematic hypoglycemic events, the child's age, duration of diabetes, insulin regimen and comorbid diseases." (PMID 22185481, 2011). "We compared MetS (pre-diabetic) and diabetic patients with patients without these conditions in order to examine the effects of the insulin-resistant state before diabetes (and anti-diabetes medication) commenced, and the effects of diabetes before heart failure developed." (PMID 21929744, 2011). "The present study sought to address this hypothesis of persistent dysregulation of gene expression for the first time with whole genome analysis of retinal transcriptome with untreated diabetes and with insulin therapy." (PMID 21575160, 2011). "Transcriptomic analysis and extensive targeted confirmations demonstrated that, although insulin normalizes expression of the majority of genes altered after three months of untreated diabetes, expression of a number of genes remain partially or totally not normalized following therapy." (PMID 21575160, 2011).
diabetes (continued). "The effect of Resv on insulin sensitivity has been the subject in nine studies using rats or mice in which insulin sensitivity was reduced by high fat diets, using animal strains prone to developing insulin resistance or by chemically induced diabetes (treatment with streptozotocin)." (PMID 21698226, 2011). "The insulin signaling pathway in diabetes mellitus type 2 is regulated by a number of transcription factors, notably HNFs, especially MODY1 (HNF4α), which regulates a large fraction of the hepatic and pancreatic transcriptomes by binding directly to approximately half of the transcribed genes." (PMID 21731631, 2011). "Moreover, his blood glucose level was elevated (400 mg/dL) and urine analysis showed glucosuria (3+); therefore, post-transplant diabetes mellitus was diagnosed and insulin therapy was commenced." (PMID 22032472, 2011). "We have previously reported the upregulation of Jak3 at three months of untreated diabetes in the STZ rat model and the failure of insulin to prevent upregulation of Jak3 suggests that insulin therapy is insufficient to prevent some aspects of retinal inflammation with diabetes." (PMID 21575160, 2011). "In diabetes, these functions of MT come to bear on insulin signaling and coronary heart disease." (PMID 21599891, 2011). "A cure for type 1 diabetes mellitus depends on replenishing functional insulin-producing cells." (PMID 21876779, 2011). "At puberty, probably due to increased b-cell apoptosis, insulin may be required in addition to thiamine treatment to control diabetes." (PMID 21448333, 2011). "Type 1 diabetes is insulin dependent, the so called insulin dependent diabetes mellitus (IDDM)." (PMID 23554718, 2011). "Gene therapy can be a successful treatment for diabetes if insulin can be produced through a glucose-regulated pathway and if the insulin thus produced can elicit responses to glucose fluctuation levels that are similar to those induced by natural insulin secretion." (PMID 22047106, 2011). "Lipohypertrophy was related significantly to the dose of insulin units per kg of body weight (Odds ratio [OR] = 16.4; 95% CI, 2.2 - 124.6; P = 0.007), the duration of diabetes, [OR] = 1.16; 95% CI, 1.05 - 1.32; P = 0.004)), and the body mass index (BMI) [OR] = 1.68; 95% CI, 1.25 - 2.15; P = 0.006)." (PMID 21838879, 2011). "In interspecies comparative studies, we have shown that such drastic morphological changes occur selectively in large islets (>50–100 μm in diameter) in humans, and similar changes are also observed in mice under conditions of an increased demand for insulin such as pregnancy, obesity and diabetes." (PMID 22102895, 2011). "As lipolysis and circulating free fatty acids increase under insulin resistance conditions, these results demonstrate that the decrease in plasma lipids may contribute to the improvement of severe diabetes, at least partially." (PMID 21375727, 2011). "It is therefore expected that the Web application could be most useful for patients who use insulin and have a recent diagnosis of diabetes." (PMID 21959968, 2011). "If you have the flu, should you stop taking your diabetes tablets or insulin?" (PMID 21166853, 2011). "Recent studies revealed that activation of constitutive androstane receptor (CAR) which is highly expressed in the liver, prevents diet-induced obesity, reduces hepatic steatosis, improves insulin sensitivity, and ameliorates diabetes and fatty liver disease in mice." (PMID 21568932, 2011). "Analysis of the data from the three month insulin intervention experiment in the context of this one month duration of diabetes experiment (i.e., prior to initiation of insulin treatment) permits further refinement of gene expression patterns into more specific Rescued and Prevented categories." (PMID 21575160, 2011).